LCTL (lactase like)
Description:
Plays a role in formation of the lens suture in the eye, which is important for normal optical properties of the lens.
Synonyms: KLPH; FLJ33279; KLG
Tractability: Antibody: UniProt predicts a signal peptide or a membrane-spanning region; the Human Protein Atlas places it where antibodies can reach.
Gene: Protein-coding gene on chromosome 15 (66,547,179 to 66,565,998, reverse strand). Ensembl gene ENSG00000188501.
Subcellular location: Endoplasmic reticulum membrane
Subcellular location (Human Protein Atlas): Plasma membrane; Endoplasmic reticulum
Gene Ontology:
Molecular function: hydrolase activity, hydrolyzing O-glycosyl compounds
Biological process: carbohydrate metabolic process; lens morphogenesis in camera-type eye
Cellular component: brush border; endoplasmic reticulum; endoplasmic reticulum membrane
Genetic constraint (gnomAD): Loss-of-function variants: 61 observed, 65.86 expected, observed/expected ratio (o/e) 0.93, 90% interval 0.75 to 1.15. The upper end of that interval is the gene's LOEUF score, 1.15, which puts it in group 5 of 6, group 1 being the genes least tolerant of losing a copy. Missense variants: 602 observed, 650.73 expected, observed/expected ratio (o/e) 0.93, 90% interval 0.86 to 0.99. Synonymous variants: 240 observed, 249.1 expected, observed/expected ratio (o/e) 0.96, 90% interval 0.87 to 1.07.
Homologues: Orthologues: chimpanzee LCTL (99% identical), dog LCTL (91% identical), pig LCTL (89% identical), mouse Lctl (84% identical), rat Lctl (81% identical), macaque LCTL (79% identical), guinea pig LCTL (76% identical), rabbit LCTL (73% identical), zebrafish lctlb (69% identical), tropical clawed frog lctl (69% identical), zebrafish lctla (62% identical), Drosophila melanogaster CG9701 (38% identical), and 2 more. Paralogues in human: LCT (44% identical), GBA3 (37% identical), KL (37% identical), KLB (37% identical).
Diseases named in the same sentence as LCTL in open-access papers:
LCTL is named in the same sentence as 7 diseases in open-access papers, as found by Europe PMC text mining. Sharing a sentence is not in itself a finding about the gene and the disease. The quoted sentences say what the papers report.
cataract (1 paper, 2025). Partial or complete opacity of the crystalline lens of one or both eyes that decreases visual acuity and eventually results in blindness. "Q6UWM7 (lactase-like protein) was significantly lower in nuclear, corticonuclear, and mixed-type cataracts than in transparent lenses and about 1.15-fold lower in corticonuclear than in cortical cataracts." (PMID 40649110, 2025). "The lactase-like protein (LCTL, UniProt ID: Q6UWM7) quantity was lower in all cataracts except for the cortical type." (PMID 40649110, 2025).
COVID-19 (1 paper, 2022). A disease caused by infection with severe acute respiratory syndrome coronavirus 2. "Higher levels of LCTL, SFTPD, KEL, and ATP2A3 were solely associated with a decreased risk of hospitalization (ORs = 0.86–0.93), whilst higher levels of ICAM-1 were solely associated with a decreased risk of respiratory support/death of COVID-19 (OR = 0.84)." (PMID 35239653, 2022).
glioma (1 paper, 2019). A benign or malignant brain and spinal cord tumor that arises from glial cells (astrocytes, oligodendrocytes, ependymal cells). "In this study, we found that the expression of LCTL is not only abnormally upregulated, but also significantly associated with WHO grade, molecular subtype, and IDH status in glioma." (PMID 31681612, 2019). "Mechanistically, LCTL might regulate the immunity in glioma through FGF signaling pathway." (PMID 31681612, 2019). "Here, we found that the endogenous expression of LCTL is regulated by promoter DNA methylation rather than genetic alterations in glioma." (PMID 31681612, 2019).
renal cell carcinoma (1 paper, 2022). "Third, although this study found that four genes (COL7A1, LCTL, NPR3, and ZFHX4), had a large impact on the prognosis of renal cell carcinoma and analyzed their relationship with survival in multiple cancers, the specific molecular biology and cell biology mechanisms need to be further investigated." (PMID 36159988, 2022).
sarcoma (1 paper, 2022). A usually aggressive malignant neoplasm of the soft tissue or bone. "The 1-year AUC values for TCGA training cohort of the SAGRI constructed using the four sarcoma-like differentiation-related genes (COL7A1, LCTL, NPR3, ZFHX4) were 0.725 in the training set, 0.712 in the internal validation set, and 0.770 in the external validation set." (PMID 36159988, 2022).
tumor (1 paper, 2019). "Collectively, these findings suggest that LCTL participates in regulating the tumor immune environment." (PMID 31681612, 2019).
LCTL also shares sentences with these, for which no sentence is quoted: cortical cataract (1 paper).